SUZ12 (SUZ12 polycomb repressive complex 2 subunit)
Description:
Polycomb group (PcG) protein. Component of the PRC2 complex, which methylates 'Lys-9' (H3K9me) and 'Lys-27' (H3K27me) of histone H3, leading to transcriptional repression of the affected target gene. The PRC2 complex may also serve as a recruiting platform for DNA methyltransferases, thereby linking two epigenetic repression systems. Genes repressed by the PRC2 complex include HOXC8, HOXA9, MYT1 and CDKN2A.
Synonyms: CHET9; JJAZ1; KIAA0160; IMMAS
Tractability: Small molecule: a structure with a bound ligand is known; a high-quality ligand is known. PROTAC: it is named in the literature on targeted protein degradation; UniProt records ubiquitination sites on it; ubiquitination databases record sites on it; its protein half-life has been measured; a small molecule that binds it is known.
Chemical probes: UNC6852 (high quality)
Gene: Protein-coding gene on chromosome 17 (31,936,995 to 32,001,045, forward strand). Ensembl gene ENSG00000178691.
Subcellular location: Nucleus
Subcellular location (Human Protein Atlas): Nuclear bodies; Nucleoli; Nucleoplasm; Nucleoli rim
Pathways (Reactome):
Disease: Defective pyroptosis; HCMV Early Events
Gene expression (Transcription): PRC2 methylates histones and DNA; Transcriptional Regulation by E2F6
Cell-Cell communication: Negative Regulation of CDH1 Gene Transcription
Cellular responses to stimuli: Oxidative Stress Induced Senescence
Chromatin organization: PKMTs methylate histone lysines
Developmental Biology: Activation of anterior HOX genes in hindbrain development during early embryogenesis
Immune System: Regulation of PD-L1(CD274) transcription
Metabolism of proteins: SUMOylation of chromatin organization proteins
Signal Transduction: Regulation of PTEN gene transcription
Gene Ontology:
Molecular function: enzyme activator activity; histone H3K9me2/3 reader activity; protein binding; transcription corepressor binding; chromatin DNA binding; chromatin binding; lncRNA binding; promoter-specific chromatin binding; RNA binding; RNA polymerase II cis-regulatory region sequence-specific DNA binding; sequence-specific DNA binding
Biological process: negative regulation of cell differentiation; heterochromatin formation; negative regulation of transcription by RNA polymerase II; chromatin organization; facultative heterochromatin formation
Cellular component: ESC/E(Z) complex; nuclear body; nucleolus; nucleoplasm; nucleus; RSC-type complex; chromatin silencing complex; PcG protein complex; protein-DNA complex; ribonucleoprotein complex; sex chromatin
Genetic constraint (gnomAD): Loss-of-function variants: 14 observed, 63.66 expected, observed/expected ratio (o/e) 0.22, 90% interval 0.14 to 0.34. The upper end of that interval is the gene's LOEUF score, 0.34, which puts it in group 1 of 6, group 1 being the genes least tolerant of losing a copy. Missense variants: 471 observed, 778.13 expected, observed/expected ratio (o/e) 0.61, 90% interval 0.56 to 0.65. Synonymous variants: 230 observed, 262.79 expected, observed/expected ratio (o/e) 0.88, 90% interval 0.79 to 0.98.
Cancer hallmarks: invasion and metastasis (promotes); proliferative signalling (promotes)
Homologues: Orthologues: macaque SUZ12 (99% identical), chimpanzee SUZ12 (99% identical), dog SUZ12 (99% identical), pig SUZ12 (99% identical), rabbit SUZ12 (99% identical), guinea pig SUZ12 (98% identical), mouse Suz12 (97% identical), rat Suz12 (97% identical), tropical clawed frog suz12 (81% identical), zebrafish suz12b (70% identical), zebrafish suz12a (65% identical), Drosophila melanogaster Su(z)12 (37% identical).
Diseases named in the same sentence as SUZ12 in open-access papers:
SUZ12 is named in the same sentence as 160 diseases in open-access papers, as found by Europe PMC text mining. Sharing a sentence is not in itself a finding about the gene and the disease. The quoted sentences say what the papers report.
breast carcinoma (36 papers, 2007 to 2025). "In support of a protective role for PRC2 in breast cancer, we found that mutations in PRC2 core components are associated with a poor prognosis and documented several mutations in EZH2 and PRC2 core component SUZ12 in breast cancer metastases." (PMID 26637281, 2015). "To exclude the system interference in HP5008 cells, we conducted CRISPR-Cas9 knockouts of Rad51b, Ezh2, Suz12 and Aebp2 in Brca1-mutant 545 cells, which were isolated from a primary mammary tumor of a Brca1-MSK mouse." (PMID 41318657, 2025). "Our transcriptome analysis also demonstrated that SUZ12 level was the most highly enhanced in CSCs of the drug-resistant breast cancer cells (TAMR and ADR)." (PMID 38664825, 2024). "It is also interesting to note that SUZ12 ChEA was also the top ENCODE and ChEA pathway in MDA-231c141 tumors, the tumors where we identified MXRA8′s potential role in breast cancer." (PMID 37762032, 2023). "The p38γ MAPK pathway has been suggested to mediate EMT of breast cancer through the p38γ MAPK/GATA3/miR-200b/Suz12." (PMID 35179516, 2022). "In the context of breast cancer, our data indicate that Suz12-deleted organoids, like Ezh2-null basal cells, displayed similarities with signatures of claudin-low breast cancers, which are thought to arise from MaSCs." (PMID 30080881, 2018). "Previous studies demonstrated high SUZ12 expression levels in aggressive tumors, such as prostatic carcinoma, breast carcinoma and nervous system carcinoma, and a marked correlation between SUZ12 expression levels and tumor malignancy." (PMID 25295075, 2014). "Polycomb-group genes such as BMI1, EZH2 and SUZ12 have repeatedly been identified as adverse prognostic factors in breast cancer." (PMID 17573968, 2007). "Moreover, the expressional levels of FOXC1 gene is negatively related with that of Polycomb group (PcG) genes, i.e., Bmi1, EZH2, and SUZ12, in breast cancer cells." (PMID 34167089, 2021). "The expression of EZH2 and SUZ12 was increased in several types of cancers such as prostate, ovarian, and breast cancers, and it initiated tumorigenesis and activated anti-drug responses through preventing the expression of differentiation-related genes and promoting stem cell-like phenotypes." (PMID 33014839, 2020). "Moreover, SUZ12 together with miR-200b is important for cancer stem cell growth and invasive ability in breast cancer cells." (PMID 28228691, 2017). "For instance, the Suz12 subunit is overexpressed in colon and breast cancers, and Ezh2 is upregulated in a number of tumors, including Hodgkin lymphoma, prostate cancer, and breast cancer." (PMID 24070194, 2013). "Forced expression of miR-200 members in mammary tumor cells with mesenchymal properties induces a less invasive, more slowly proliferating, partially epithelial phenotype and modifies the profile of expressed miRNAs and protein-coding genes, including many genes regulated by SUZ12." (PMID 34884985, 2021). "SUZ-12 has been identified at the breakpoints of a recurrent chromosomal translocation and may be involved in chromatin silencing and has been shown to contribute to epithelial to mesenchymal transition in breast cancer." (PMID 32784600, 2020). "The observation that Suz12 deficiency in normal mammary cells leads to de-repression of cdkn2a, paralleling that seen with loss of Ezh2, would predict that loss of PRC2 function in breast cancer would result in decreased tumor proliferation via up-regulation of p16Ink4a and p14Arf expression." (PMID 30080881, 2018). "The effects of Suz12 on e-cadherin in particular may contribute to the invasive and metastatic potential of breast carcinoma, with high miR200, low Suz12 and high e-cadherin levels associated with primary tumors and low miR200, high Suz12, and low e-cadherin observed in metastatic tumors." (PMID 24213119, 2011).
breast carcinoma (continued). "For instance, AMPK phosphorylated EZH2 at T311 to disrupt the interaction between EZH2 and SUZ12 thereby attenuating PRC2-dependent methylation of histone H3 at Lysine 27 in ovarian and breast cancer." (PMID 40289112, 2025). "We determined that 106 of these genes, including breast cancer type 1 (BRCA1), SUZ12 polycomb repressive complex 2 subunit (SUZ12), and FA complementation group M (FANCM), were involved in the cell cycle process." (PMID 38514462, 2024). "Conversely, in human breast cancer cell lines, DDX21 also participates in transcriptional repression at the SNAIL promoter by recruiting SUZ12 from the PRC2 complex to induce histone H3K27 trimethylation (H3K27me3), suppressing SNAIL expression." (PMID 39769343, 2024). "A significant correlation with poor prognosis was also observed for high EZH2 and SUZ12 expression in sarcoma and in lung adenocarcinoma; for EZH2 in breast cancer; for EZH2 and EED expression in ovarian cancer." (PMID 34202528, 2021). "Activated AMPK has also been reported to disrupt the interaction between EZH2 and the suppressor of zeste 12 (SUZ12) by phosphorylating EZH2 in ovarian and breast cancer cells." (PMID 34815475, 2021). "Suppression of breast cancer cell stemness by miR-200 involves their direct targeting of mRNAs coding for BMI1 and SUZ12, which are components of polycomb group complexes 1 and 2 (PRC1 and PRC2), respectively." (PMID 34884985, 2021). "In a study using the EZH2 inhibitor 3-deazaneplanocin A (DZNep), it was found that its treatment depleted breast carcinoma cells of the PRC2 complex members (EZH2, SUZ12, and EED),and subsequently reactivated expression of IGFBP-3." (PMID 28042859, 2016). "DZNep(3- Deazaneplanocin), a compound that disrupts the PRC2, effectively depletes EZH2, Suz12, and EED and inhibits H3K27me3 in breast cancer and AML cells." (PMID 23985559, 2013). "SUZ12 and EZH2 occupancy, along with E-box motifs and MYC occupancy, and H3K27me3 marks at the regulatory region of the ZNF148 locus provide a possible mechanism for MYC-induced repression of ZNF148 in breast cancer." (PMID 36207293, 2022). "Treatment of ErbB2-driven breast cancer cells with the biguanide phenformin, which directly inhibits OXPHOS regardless of the presence of c-Src, activated AMPK and inhibited mTORC1, markedly reducing Ezh2 and Suz12 protein expression." (PMID 31263101, 2019). "In addition, others have demonstrated that the polycomb repressor complex 2 (PRC2), including binding of SUZ12 and EZH2 to the PGR promoter, contributes to PGR transcriptional repression in breast cancer cells." (PMID 25229191, 2014). "Additionally, DDX21 interacts with EZH2 and SUZ12 at the SNAIL promoter to enhance H3K27me3, epigenetically repressing SNAIL transcription and thereby inhibiting epithelial–mesenchymal transition (EMT) and suppressing breast cancer cell invasion and metastasis." (PMID 39769343, 2024). "However, in the current study we found that SUZ12 was not binding with EZH2, indicating the PRC2-independent action of EZH2 in PDAC as reported in breast cancer." (PMID 34771469, 2021).
endometrial stromal sarcomas (26 papers, 2010 to 2025). "Another gene in this list is SUZ12, which is associated with diseases including endometrial stromal sarcoma and endometrial stromal nodules." (PMID 31552180, 2019). "SUZ12, a gene identified at the breakpoints of a recurrent chromosomal translocation reported in endometrial stromal sarcoma, encodes for a zinc finger protein belonging to the Polycomb Repressive Complex 2 (PRC2), which modulates chromatin structure by repressive mechanisms." (PMID 27792997, 2016). "Genetic mutations of SUZ12, a PRC2 component supporting EZH2 activation, are highly detected in the endometrial stromal sarcoma with increased stromal proliferation." (PMID 37198149, 2023). "To this end, we generated the endometrial stromal sarcoma associated JAZF1-SUZ12 fusion and investigated how FBXW7 affects its protein level compared to intact JAZF1 and SUZ12." (PMID 35328741, 2022). "Fusion of JAZF to SUZ12 often occurs in endometrial stromal sarcoma, but the effects of JAZF1-SUZ12 on chromatin and cell differentiation are not understood." (PMID 35649353, 2022). "Some studies showed that SUZ12 has been subjected to chromosomal aberrations in endometrial stromal sarcomas (ESS)." (PMID 27471434, 2016). "Endometrial stromal sarcoma (ESS) is a malignancy of the uterus that had been previously linked with recurrent fusions: the fusion of JAZF1, a transcriptional repressor, with members of the polycomb complex including SUZ12, PHF1, and EPC1." (PMID 25676695, 2015). "For example, chimeric RNAs of well-known fusions such as JAZF1-JJAZ1 (SUZ12) and PAX3-FOXO1 are sometimes expressed in the normal cells, despite being frequently detected in endometrial stromal sarcomas and alveolar rhabdomyosarcomas, respectively." (PMID 38919532, 2024). "In low-grade endometrial stromal sarcoma (LG-ESS), the PRC2 subunit SUZ12 is often fused with the NuA4/TIP60 subunit JAZF1." (PMID 35649353, 2022). "The majority of low-grade endometrial stromal sarcomas (LG-ESSs) harbor a fusion gene, most commonly involving JAZF1, SUZ12, and/or PHF1 genes, i.e., JAZF1-SUZ12 fusion (80%), JAZF1-PHF1 fusion (6%), or EPC1-PHF1 fusion (4%)." (PMID 32921307, 2020). "Recently, we provided evidence that expression of a designer chimeric RNA targeting JAZF1 and SUZ12 genes in human endometrial stromal cells also drives the formation of JAZF1-SUZ12, a cancer fusion gene commonly found in low-grade endometrial stromal sarcomas patients." (PMID 35326453, 2022).
gastric cancer (20 papers, 2016 to 2024). A primary or metastatic malignant neoplasm involving the stomach. "There was significant SUZ12 up regulation in gastric cancer (GC) tissues that was associated with distant metastasis, tumor size, stage, and lower survival." (PMID 37807067, 2023). "EZH2, NFE2L2, REST, SMAD4 and SUZ12 were all implicated as common transcriptional regulators of DEGs in glioma, sarcoma, breast and stomach cancers, suggesting that altered AMPK signaling converged on similar groups of transcriptional targets." (PMID 32807122, 2020). "Loss of SUZ12 has been linked directly to increased metastasis in gastric cancer and non-small cell lung cancer, suggesting that the multiple tumor foci with the same histology could in part be due to early dissemination from a single primary tumor." (PMID 32651197, 2020). "Previous studies have revealed that SUZ12 expression associates with patients’ prognosis and is identified as a key independent prognostic predictor for patients with epithelial ovarian cancer, non-small cell lung cancer and gastric cancer." (PMID 28228691, 2017). "A recent study demonstrates that HMGA1 stimulates gastric cancer proliferation and metastasis via transactivating SUZ12 and CCDC43 expression." (PMID 38706894, 2024). "MiR-362-5p also enhances the cisplatin sensitivity of gastric cancer cells via SUZ12 polycomb repressive complex 2 subunit (SUZ12)." (PMID 35365168, 2022). "The high expression of LINC00659 can promote the proliferation, metastasis and invasion of gastric cancer, which is related to the promotion of SUZ12 transcription factor expression." (PMID 33145980, 2020). "Present studied have shown that SUZ12 is associated with tumour proliferation and invasion in lung cancer, gastric cancer, colon cancer, whereas the deletion of SUZ12 gene can significantly inhibit tumour transformation." (PMID 33145980, 2020). "Through a CHIP-Seq experiment, this SNP was found to bind to SUZ12 protein, which promoted gastric cancer cell invasion." (PMID 32725141, 2020). "SUZ12 promotes proliferation and metastasis in many cancers, including gastric cancer, colorectal cancer, ovarian cancer, bladder cancer, and NSCLC." (PMID 31552180, 2019). "However, studies have shown that SUZ12 promotes the EMT process in gastric cancer and bladder cancer cells." (PMID 39400513, 2024). "Moreover, USP3 interacts with SUZ12 in gastric cancer and regulates the homeostasis of SUZ12 through deubiquitylation, thereby promoting the migration and invasion of gastric cancer cells." (PMID 38531846, 2024). "SUZ12 has been known to promote the proliferation of gastric cancer and also in metastasis." (PMID 30644396, 2019). "Moreover, DUXAP8 was also found to be over-expressed in human gastric cancer, and increased DUXAP8 promoted cells proliferation and invasion through epigenetically silencing PLEKHO1 expression by binding with EZH2 and SUZ12 in gastric cancer cells." (PMID 29152119, 2017). "Furthermore, to investigate the roles of EZH2/SUZ12 in gastric cancer, we performed qRT-PCR analysis and found that EZH2/SUZ12 expression was significantly increased in 30 pairs of gastric cancer tissues." (PMID 27036039, 2016). "Additionally, LINC00659 could regulate cell cycle and invasion of gastric cancer by promoting the expression of SUZ12." (PMID 33145980, 2020). "There is evidence showed that its expression is diminished in multiple cancers and possesses tumor-suppressor features for its inhibitory effects on cell proliferation, and our previous study showed that SUZ12 could repress its expression in gastric cancer cells." (PMID 27246976, 2017). "Studies reported that SUZ12 knockdown inhibited the proliferation, colony formation, invasion and migration of HNSCC and gastric cancer cells." (PMID 39400513, 2024). "SUZ12 expression was reported to be up‐regulated in head and neck squamous carcinoma (HNSCC), ovarian cancer, gastric cancer tissues etc., and correlated with a poor prognosis." (PMID 39400513, 2024).
bladder cancer (19 papers, 2015 to 2025). "On the other hand, MALAT1 in bladder cancer cells is reported to associate with a polycomb repressive component, SUZ12." (PMID 27250026, 2016). "However, zebrafish is unlikely to be a good model of some tumors commonly associated with suz12 mutations, such as penile, endometrial, and bladder carcinomas." (PMID 32651197, 2020). "In human bladder cancer, gene sets associated with H3K27me3 and PRC2 (SUZ12/EED) targets were also positively enriched in KMT2C/D mutant samples." (PMID 39806204, 2025). "Among them, SUZ12 is considered an important oncogene involved in several cancers such as bladder cancer, non‐small cell lung cancer, and ovarian cancer, and is currently a research hotspot in targeted therapy for various types of tumours." (PMID 40478202, 2025). "In bladder cancer, circSTX6 increases the expression of SUZ12 by sponging miR‐515‐3p and interacting with the mRNA stabilizer PABPC1, enhancing the chemoresistance of bladder cancer cells to cisplatin by facilitating DNA damage repair and inhibiting apoptosis." (PMID 39901896, 2025). "A recent study showed that the MALAT1 expression level was upregulated and promoted the activity of the PRC2 complex by interacting with the SUZ12 protein in bladder cancer." (PMID 28412742, 2017). "Specifically, EZH2 mediates the role of the MALAT1–PRC2 partnership in the epithelial–mesenchymal transition in renal cell carcinoma, whereas SUZ12 promotes the role of the MALAT1-PRC2 binding in tumor metastasis in bladder cancer." (PMID 27998273, 2016). "We also found that the protein level of SUZ12 was upregulated in bladder cancer tissues." (PMID 38163881, 2024). "MALAT1 also bound to SUZ12, thus promoting bladder cancer metastasis." (PMID 32393270, 2020). "In literature, correlation between elevated EZH2, SUZ12 and/or EED gene expression and poor prognosis of bladder carcinoma were reported." (PMID 36428492, 2022). "Moreover, in bladder cancer, overexpressed MALAT1 promotes TGFβ-driven bladder cancer metastasis by directly interacting with PRC2 subunit Suz12 to repress E-cadherin expression." (PMID 29685978, 2018). "One study demonstrates previously that MALAT1 associates with PRC2 by interacting with SUZ12 but not EZH2 and that inhibition of MALAT1 decreases the binding of SUZ12 to the E-cadherin gene promoter in bladder cancer." (PMID 26516927, 2015). "Recent studies indicate that MALAT1 enhances the activity of the PRC2 complex in bladder cancer by interacting with the subunit SUZ12 but not the subunit EZH2 in PRC2." (PMID 26516927, 2015).